ACTG1 (actin gamma 1)
Diseases named in the same sentence as ACTG1 in open-access papers (continued):
Sharing a sentence is not in itself a finding about the gene and the disease.
tumor (30 papers, 2012 to 2025). "Studies have found that RRAD can inhibit tumour cell proliferation, migration and Warburg effect by downregulating ACTG1 expression." (PMID 36934248, 2023). "Sequencing the Actin genes (ACTB and ACTG1) from the tumor organoid derived from patient 8, the source of the PCs encoding antibody 8-3, showed no mutations in the protein-coding regions, verifying the self-antigen nature." (PMID 37751306, 2023). "ACTG1 knockdown prevents tumor cells from migrating, proliferating, and repairing wounds via the ROCK signaling system." (PMID 37520321, 2023). "Clinically, ACTG1 gains predicted poor prognosis in UCECs, which was also supported by enrichments of tumor-promoting pathways in the same samples." (PMID 33217970, 2020). "One such issue is the influence of knockout of ACTB or ACTG1 on the cell proliferation rate, signaling pathways involved in tumor progression, and nuclear processes regulated by actin." (PMID 32326615, 2020). "High expression of ACTG1 is significantly correlated with advanced tumor stages and poor prognosis in patients with HCC." (PMID 33260154, 2020). "To explore the possible role of protein lactylation in driving tumor cell proliferation, we then focused on the Hippo signaling pathway, in which several components or regulatory proteins, such as ACTG1, MOB1A, PPP1CA, YAP, and TEAD1, were found to be lactylated." (PMID 38512451, 2024). "Since ACTG1 predicted poor prognosis and was associated with pro-tumorigenic signaling pathways such as cell cycle, PRC2, and EMT, we also postulated that ACTG1 may regulate cell-intrinsic properties required for tumor cell fitness." (PMID 33217970, 2020). "Given that ACTG1 gains were associated with worse prognosis, we sought to further explore the genetic interactions of ACTG1 based on known classifications of UCEC including FIGO Stage, histological grade, molecular subtypes, and tumor type." (PMID 33217970, 2020). "Enriched in UCEC with ACTG1 gains, EMT regulates tumor evasion of innate immunity or immune therapies." (PMID 33217970, 2020). "Among the genes, ACTG1, CAT, and RAF1 were upregulated in tumor tissues relative to normal tissues." (PMID 38806963, 2024). "Moreover, our results showed that ACTG1, CSNK1D, PPP1CC, and BIRC5 expression was negatively correlated with miR-497-5p expression in HCC tumor biopsies (n = 364, r = −0.32, -0.29, -0.24, and -0.33, respectively, p < 0.001)." (PMID 33816607, 2021). "Furthermore, we showed that IL6, CASP3, ACTB, ACTG1 and RAP1B are hub genes that regulate the tumour metastasis regulation network." (PMID 33759378, 2021). "In contrast, ACTG1 was stained moderately in 13/20 (~65%) adjacent non‐tumour tissues and showed negative or low expression in the majority of the RCC tissues and lung metastasis tissues." (PMID 33759378, 2021). "Moreover, while we further looked at ACTG1 gains among tumors with distinct histologic grades, we found ACTG1 gains in greater proportion in grade III neoplasms and had reduced representation in grade I neoplasms." (PMID 33217970, 2020). "In addition, six genes, KRT18, ARPC5L, ACTG1, ARPC2, EZR, and YWHAZ, were simultaneously enriched in tumors and tumor tissues highly expressing TNFRSF11B, which may enhance pathogenic E. coli focal adhesion, actin filament binding, and cadherin binding, as demonstrated by GO functional analysis." (PMID 34938284, 2021).
infection (5 papers, 2013 to 2025). The state of being infected such as from the introduction of a foreign agent such as serum, vaccine, antigenic substance or organism. "ACTG1 (actin, cytoplasmic type 5) was downregulated by rNS1-SD30 infection at 12 h, and upregulated upon infection with both viruses at 24 and 36 h compared with uninfected controls." (PMID 29492200, 2018). "The fact that angiopoietin is known to limit the formation of actin stress fibres correlates well with our findings that at 48 h post infection transcription of ANGPTL4 further increased and transcription of gamma actin (ACTG1 and ACTG2) declined." (PMID 23326599, 2013).
myopathy (2 papers, 2017 to 2021). A disease of the muscle in which the muscle fibers do not function properly. "The absence of ACTG1 resulted in muscle weakness and a progressive myopathy in mice; meanwhile, the reduced expression of ACTG1 was closely associated with up-regulated MYH3 induced by RSV." (PMID 35036414, 2021).
neurodevelopmental disorder (2 papers, 2025). A behavioral and cognitive disorder with onset during the developmental period that involves impaired or aberrant development of intellectual, motor, or social functions. "Group 1—Severe multisystem neurodevelopmental disorders (Transcriptional/RNA-processing phenotype): This group included patients carrying variants in POLR1C, TCF4, HNRNPU, NIPBL, and ACTG1." (PMID 41300846, 2025).
ACTG1 also shares sentences with these, for which no sentence is quoted: developmental delay (3 papers); autosomal dominant deafness (2); brain malformations (2); cardiomyopathies (2); COVID-19 (2); diffuse large B-cell lymphoma (2); genetic disorder (2); Hearing impairment (2); hematological malignancies (2); hypertrophic cardiomyopathy (2); Myocardial fibrosis (2); actinopathies (1); age-related hearing loss (1); arrhythmogenic right ventricular cardiomyopathy (1); autism (1); B-cell neoplasm (1); Bartter syndrome type 4 (1); blood cancers (1); Brachycephaly (1); carcinosarcoma (1); cardiac hypertrophy (1); cervical squamous cell carcinoma (1); colon adenocarcinoma (1); colorectal adenocarcinoma (1); Cornelia de Lange syndrome (1); dental caries (1); diabetic kidney disease (1); diabetic retinopathy (1); endometrioid carcinomas (1); eye cancer (1).
A further 32 diseases each share a sentence with ACTG1 in 1 paper.